GPR88 (G protein-coupled receptor 88)
Description:
Orphan G protein-coupled receptor implicated in a large repertoire of behavioral responses that engage motor activities, spatial learning, and emotional processing (By similarity). May play a role in the regulation of cognitive and motor function (By similarity). Couples with the heterotrimeric G protein complex of the G(i) subfamily, consisting of GNAI1, GNB1 and GNG2, thereby acting through a G(i)-mediated pathway. Plays a role in the attenuation of D1 dopamine receptor (D1R)-mediated cAMP response in ciliated cells. In non-ciliated cells, involved in the inhibition of the beta-2 adrenergic receptor (B2AR) response.
Synonyms: STRG; COCPMR
Tractability: Small molecule: a structure with a bound ligand is known; a high-quality ligand is known; it belongs to a druggable protein family. Antibody: UniProt places it where antibodies can reach, with medium confidence; UniProt predicts a signal peptide or a membrane-spanning region; its Gene Ontology location is reachable by antibodies, with medium confidence. PROTAC: a small molecule that binds it is known.
Target class: Family A G protein-coupled receptor; Membrane receptor
Chemical probes: BI-9808 (high quality)
Gene: Protein-coding gene on chromosome 1 (100,538,139 to 100,542,021, forward strand). Ensembl gene ENSG00000181656.
Subcellular location: Cell membrane; Cell projection, cilium membrane; Cytoplasm; Nucleus
Gene Ontology:
Molecular function: beta2-adrenergic receptor activity; cytoskeletal motor activity; G protein-coupled photoreceptor activity; G protein-coupled receptor activity
Biological process: adenylate cyclase-modulating G protein-coupled receptor signaling pathway; G protein-coupled receptor signaling pathway; cellular response to light stimulus; motor learning; phototransduction; adrenergic receptor signaling pathway; detection of visible light
Cellular component: ciliary membrane; cilium; heterotrimeric G-protein complex; plasma membrane; cytoplasm; nucleus; membrane
Genetic constraint (gnomAD): Loss-of-function variants: 18 observed, 14.63 expected, observed/expected ratio (o/e) 1.23, 90% interval 0.85 to 1.77. The synonymous counts are far from expectation, so gnomAD's model fits this gene poorly and the ratio says little. Missense variants: 430 observed, 382.71 expected, observed/expected ratio (o/e) 1.12, 90% interval 1.04 to 1.22. Synonymous variants: 307 observed, 209.45 expected, observed/expected ratio (o/e) 1.47, 90% interval 1.33 to 1.61.
Homologues: Orthologues: chimpanzee GPR88 (100% identical), macaque GPR88 (99% identical), pig GPR88 (98% identical), rabbit GPR88 (97% identical), dog GPR88 (97% identical), mouse Gpr88 (96% identical), rat Gpr88 (95% identical), tropical clawed frog gpr88 (40% identical). Paralogues in human: MTNR1B (19% identical), MTNR1A (18% identical), PRLHR (17% identical), NPY2R (16% identical), GPR50 (16% identical), NPY4R2 (15% identical), GPR75 (15% identical), NPY1R (15% identical), NPY4R (15% identical), TACR2 (15% identical), NPY5R (14% identical), PROKR2 (14% identical), and 21 more.